PARS2 (prolyl-tRNA synthetase 2, mitochondrial)
Description:
Mitochondrial aminoacyl-tRNA synthetase that catalyzes the specific attachment of the proline amino acid (aa) to the homologous transfer RNA (tRNA), further participating in protein synthesis. The reaction occurs in a two steps: proline is first activated by ATP to form Pro-AMP and then transferred to the acceptor end of tRNA(Pro).
Synonyms: ProRS; DKFZp727A071; DEE75; EIEE75; MT-PRORS
Tractability: PROTAC: ubiquitination databases record sites on it; its protein half-life has been measured.
Gene: Protein-coding gene on chromosome 1 (54,756,594 to 54,764,546, reverse strand). Ensembl gene ENSG00000162396.
Subcellular location: Mitochondrion matrix
Subcellular location (Human Protein Atlas): Mitochondria; Nucleoli fibrillar center
Pathways (Reactome):
Metabolism of proteins: Mitochondrial tRNA aminoacylation
Gene Ontology:
Molecular function: proline-tRNA ligase activity; aminoacyl-tRNA ligase activity; ATP binding; nucleotide binding
Biological process: prolyl-tRNA aminoacylation; tRNA aminoacylation for protein translation
Cellular component: mitochondrion; cytoplasm; mitochondrial matrix
Genetic constraint (gnomAD): Loss-of-function variants: 22 observed, 32.16 expected, observed/expected ratio (o/e) 0.68, 90% interval 0.49 to 0.98. The upper end of that interval is the gene's LOEUF score, 0.98, which puts it in group 4 of 6, group 1 being the genes least tolerant of losing a copy. Missense variants: 585 observed, 633.18 expected, observed/expected ratio (o/e) 0.92, 90% interval 0.86 to 0.99. Synonymous variants: 240 observed, 260.76 expected, observed/expected ratio (o/e) 0.92, 90% interval 0.83 to 1.02.
Gene-disease validity (ClinGen):
ClinGen rates the evidence that PARS2 causes each of these diseases.
mitochondrial disease (autosomal recessive): Moderate.
Homologues: Orthologues: chimpanzee PARS2 (99% identical), macaque PARS2 (95% identical), dog PARS2 (85% identical), rabbit PARS2 (82% identical), guinea pig PARS2 (82% identical), mouse Pars2 (82% identical), pig PARS2 (80% identical), rat Pars2 (79% identical), zebrafish pars2 (59% identical), tropical clawed frog pars2 (58% identical), Drosophila melanogaster ProRS-m (40% identical), Caenorhabditis elegans pars-2 (32% identical). Paralogues in human: TARS3 (21% identical), TARS2 (20% identical), TARS1 (18% identical), MRPL39 (9% identical).
Diseases named in the same sentence as PARS2 in open-access papers:
PARS2 is named in the same sentence as 41 diseases in open-access papers, as found by Europe PMC text mining. Sharing a sentence is not in itself a finding about the gene and the disease. The quoted sentences say what the papers report.
Alpers syndrome (5 papers, 2015 to 2024). A cerebral degeneration that results in progressive degeneration of grey matter in the cerebrum and has_symptom convulsions. "Similarly, mutation of mitochondrial prolyl-tRNA synthetase 2 (PARS2), which is associated with neurological diseases such as Alpers syndrome and some infantile-onset neurodegenerative disorders, is also accompanied by delayed myelinating phenotypes." (PMID 36548190, 2022). "Variants in PARS2, CARS2, GABRB2, FARS2, and NARS2 were also reported in Alpers’ syndrome patients." (PMID 34690748, 2021). "In recent years, with the advancement of genetic testing technology, Alpers syndrome caused by NON-POLG genes has also been continuously reported, including mitochondrial aminoacyl transfer RNA synthetase related genes (PARS2, CARS2, FARS2 and NARS2) and γ-GABA receptor related genes Gene (GABRB2)." (PMID 34690748, 2021). "In terms of therapy, whereas valproate is contraindicated in other mitochondrial encephalopathies, such as Alpers syndrome due to pathogenic variants in POLG (DNA polymerase γ), as it can lead to fulminant liver failure, there are no definite data on valproate toxicity in PARS2‐related DEE." (PMID 38087948, 2024).
developmental delay (3 papers, 2018 to 2024). "PARS2 deficiency was characterized as a neurodevelopmental and neurodegenerative disorder with early-onset seizures and global developmental delay." (PMID 39253392, 2024). "These diseases display a broad clinical spectrum and may be further complicated with other symptoms such as developmental delay (NARS2, PARS2), pontocerebellar hypoplasia (RARS2), visual impairment (FARS2) psychomotor delay (TARS2) and microcephaly (VARS2)." (PMID 29288497, 2018).
hypertrophic cardiomyopathy (3 papers, 2015 to 2024). A condition in which the myocardium is hypertrophied without an obvious cause. "Cardiac involvement is commonly observed in patients with pathological variants of PARS2, usually with initial hypertrophic cardiomyopathy followed by a dilatative evolution in a brief time before death usually occurring in childhood." (PMID 38087948, 2024).
malaria (3 papers, 2015 to 2022). Malaria is a serious and sometimes fatal disease caused by a parasite that commonly infects a certain type of mosquito which feeds on humans. "Adaptive variants related to malaria and glucose metabolism were identified in the Dai population and indicate the adaptation to thalassemia and G6PD deficiency resulting from malaria resistance, while selection on PARS2 is likely related to the perception of bitterness." (PMID 35864541, 2022).
cardiomyopathy (2 papers, 2015 to 2024). A disease of the heart muscle or myocardium proper. "Consequently, more patients need to be identified to determine whether gray matter degeneration with either tubulopathy or cardiomyopathy are hallmarks of defects in NARS2 and PARS2, respectively, or just examples of a wider clinical spectrum." (PMID 25629079, 2015).
microcephaly (2 papers, 2021 to 2022). A congenital or acquired developmental disorder in which the circumference of the head is smaller than normal for the person's age and sex. "This nonpolar amino acid has been linked to seizures and cognitive dysfunction, as well as to PYCR2 gene expression linked to microcephaly and hypomethylation, along with the PARS2 gene related to infantile-onset encephalopathy." (PMID 35629950, 2022).
Ataxia (1 paper, 2024). Ataxia refers to impaired coordination of voluntary muscle movement. "NARS2 and PARS2 pathogenic variants caused Alpers–Huttenlocher syndrome with ataxia." (PMID 38869703, 2024). "On the other hand, the loss of function of DARS, RARS, KARS, HARS1, SARS, and NARS2/PARS2 were reported to cause neurological diseases that share ataxic feature, indicating an important role of ARS function in the pathogenesis of ataxia." (PMID 38869703, 2024).
CLN7 disease (1 paper, 2021). "We identified other inherited metabolic disorders including pyridoxine-dependent epilepsy (PDE) due to biallelic variants in ALDH7A1, PYCR2 disease, EARS2 disease, PARS2 disease, CLN7 disease, and glucose transporter 1 deficiency syndrome with or without liver dysfunction in our study cohort." (PMID 34440401, 2021).
developmental and epileptic encephalopathies (1 paper, 2024). "Pathogenic biallelic mutations in the mitochondrial prolyl-tRNA synthetase 2 gene (PARS2) have been identified as causative factors for a specific subtype of developmental and epileptic encephalopathies (DEE) characterized by sleep-related spikes." (PMID 39061374, 2024).
Hypsarrhythmia (1 paper, 2024). Hypsarrhythmia is abnormal interictal high amplitude waves and a background of irregular spikes. "It is known that DEE with hypsarrhythmia can progress to DEE‐SWAS, an age‐dependent syndrome that typically occurs between the age of 4 and 8 years, but this has never been reported in PARS2‐related DEE." (PMID 38087948, 2024).
liver failure (1 paper, 2024). A liver disease characterized by the liver losing or has lost all of its function. "In Ciara and coauthors, a patient with different compound heterozygosity of PARS2 was treated with valproic acid, which appeared to be associated with clinical worsening and liver failure." (PMID 38087948, 2024).
metabolic disorder (3 papers, 2021 to 2025). "Therefore, an inherited metabolic disorder was suspected and whole-exome sequencing was performed, revealing a novel compound heterozygous variant of c.953C>T and c.283G>A on PARS2." (PMID 39253392, 2024). "Notably, movement disorders are often associated with metabolic diseases and have been described in conditions related to deficiencies in other aminoacyl-tRNA synthetases, including WARS2, CARS2, PARS2, RARS2, and AARS2." (PMID 41002930, 2025).
infection (1 paper, 2023). The state of being infected such as from the introduction of a foreign agent such as serum, vaccine, antigenic substance or organism. "PARS2 and EARS2 appear to exert pan-coronavirus antiviral activity as the screen showed sensitization to cell death upon infections with SARS-CoV-2, HKU5-SARSCoV-1-S, and MERS-CoV." (PMID 38108455, 2023).
mitochondrial disease (1 paper, 2022). "Other genes with contributing missense variants in JIP were PARS2, associated with mitochondrial disease, and HLA-DRA, which plays a key role in the human immune system." (PMID 35864541, 2022). "In our study, we profiled PARS2, which is associated with mitochondrial disease, as an extremely differential gene in JIP." (PMID 35864541, 2022).
PARS2 also shares sentences with these, for which no sentence is quoted: epilepsy (2 papers); Epileptic encephalopathy (2); neurological diseases (2); tumor (2); Brain atrophy (1); breast carcinoma (1); cancer (1); chronic rhinosinusitis (1); coccidiosis (1); G6PD deficiency (1); heart failure (1); infantile spasms (1); lactic acidosis (1); Leigh syndrome (1); leukodystrophies (1); liver dysfunction (1); mitochondrial encephalopathies (1); movement disorder (1); myeloma (1); ovarian failure (1); Perrault syndrome 4 (1); pyridoxine-dependent epilepsy (1); renal disease (1); sensorineural hearing loss with (1); thalassemia (1); type 2 diabetes (1); viral infection (1).